CTSS (cathepsin S)
Diseases named in the same sentence as CTSS in open-access papers (continued):
Sharing a sentence is not in itself a finding about the gene and the disease.
tumor (continued). "Studies suggest that cathepsin S promotes tumor invasion through degradation of the extracellular matrix and the release of matrix-derived growth factors, which in turn enhance angiogenesis." (PMID 40761244, 2025). "Recent findings indicate that a plethora of tumor cells produce excessive cathepsin S, which has a significant impact on the tumor microenvironment (TME)." (PMID 41026370, 2025). "Our findings indicate that CTSS-mediated autophagy significantly influences tumor immunity within the CRC microenvironment." (PMID 40794185, 2025). "To further investigate CTSS-mediated tumor immunity, we assessed CD4+ T-cell and M2 macrophage (CD163+ cells) infiltration in MC38 tumors." (PMID 40794185, 2025). "In vivo and in vitro studies using a mouse OC tumor model showed that CTSS-knockdown inhibited tumor growth and enhanced CD8+ T cell proliferation." (PMID 40707961, 2025). "A syngeneic mouse model was developed with the implantation of the 4-NQO-induced mouse OC cell line NHRI-HN1 to confirm the inhibitory role of CTSS in anti-tumor T cells." (PMID 40707961, 2025). "In vivo, CTSS suppression inhibited tumor growth and enhanced CD8+ T-cell infiltration and activity." (PMID 40794185, 2025). "High cathepsin S expression at the primary tumor site correlates with decreased brain metastasis-free survival in breast cancer patients." (PMID 41463352, 2025). "To evaluate the role of CD8+ T-cells in CTSS-mediated tumor immunity, we administered anti-CD8 antibodies (Anti-mCD8-mIgG2a InvivoFit) in an orthotopic CRC mouse model." (PMID 40794185, 2025). "Cathepsin S (CTSS) is a cysteine protease that played diverse roles in immunity, tumor metastasis, aging and other pathological alterations." (PMID 38725007, 2024). "Recent studies have shown that inhibition of CTSS reduces angiogenesis, increases apoptosis, and reduces tumour volume and invasion." (PMID 39712508, 2024). "Several cathepsins, some of which have reported roles in the degradation of extracellular proteins, were up-regulated in tumour samples, including the secreted thiol proteases cathepsin B (2.1-fold) and cathepsin S (1.7-fold)." (PMID 37397358, 2023). "Mice treated with CTSS inhibitor or anti-PD-1 monotherapy had significantly decreased tumor growth and better survival compared to control mice." (PMID 37173324, 2023). "CTSS has been shown to be secreted extracellularly as the proenzyme in a range of cell types including macrophages and tumour cells." (PMID 38116078, 2023). "As stated, CTSS has been shown to play an important role in facilitating tumour cell invasion through proteolytic action upon the basement membrane (BM) and the ECM." (PMID 38116078, 2023). "CTSS has been shown to possess gelatinolytic and collagenolytic activity, as evidenced in the tumour microenvironment wherein it contributes to the degradation of extracellular matrix and subsequent cell migration and invasion." (PMID 38116078, 2023). "Mice treated with CTSS inhibitors had slowed tumor growth and better survival compared to control mice." (PMID 37173324, 2023). "This approach should ensure effective CDN release both in tumour cells and in dendritic cells, which rely on proteases such as cathepsin S and capthesin L for antigen processing." (PMID 35606429, 2022). "We identified Cathepsin S (CTSS), which is from the Cathepsin family of cysteine proteases, has been implicated in an important role for tumor development and progression, as a MEOX2 downstream target." (PMID 35436995, 2022). "It is evident that CTSS is highly correlated with tumour invasion and migration and plays a pro-cancer role in most tumours." (PMID 35264209, 2022). "CTSS is a lysosomal cysteine protease located at the lysosome and cytoplasm; however, it can be secreted into the tumor microenvironment to induce tumor invasion, angiogenesis, and metastasis." (PMID 35436995, 2022).
tumor (continued). "In separate tissue sections from the same patients, cathepsin S was identified within keratin-positive cells (CK5+) indicating that cathepsin S was expressed by both tumor cells and macrophages within the oral SCC microenvironment." (PMID 34572924, 2021). "Among these cysteine proteinases, lysosomal CTSB, CTSD, CTSL, and CTSS have been shown to be involved in tumor malignant progression and are potential targets of anti-tumor therapy." (PMID 34923982, 2021). "Depletion of CD4+ T cells in VavP-Bcl2/CTSS chimera models confirm that CTSS is essential to support the communication and co-stimulatory signals between tumor B cells and CD4+ cells in the GC context." (PMID 34335584, 2021). "For instance, cathepsin S type is involved in tumor progression, angiogenesis, tumor growth, similarly, cathepsin L is involved in neovascularization, migration, and invasion processes as well." (PMID 34572798, 2021). "We found that neither the deletion of CTSS nor a single dose of the cathepsin S inhibitor, LY3000328, affected the tumor volume; therefore, the mechanism of preventing the expression or inhibiting cathepsin S is antinociceptive." (PMID 34572924, 2021). "A number of clinical and laboratory studies have shed lights on the function of CTSS in promoting the proliferation of tumor cells." (PMID 33912521, 2021). "The deletion of cathepsin S specifically from HSC-3 tumor cells resulted in a reduction of mechanical allodynia and thermal hyperalgesia (58.7% and 87.0%, respectively) produced by paw xenografts." (PMID 34572924, 2021). "Cathepsin S produced by tumor cells promotes tumor cell extravasation by accelerating the proteolysis of adhesion molecules between endothelial cells." (PMID 33537237, 2020). "The network associated with regulation of tissue invasion by tumor cell lines and lipid export was connected by five proteins: ACAT1, CAV1, CTSS, S100A12, and S100A9." (PMID 33607292, 2020). "High expression of CTSS in different cancers, including GB, is a dangerous factor that can contribute to tumor proliferation, migration and invasion." (PMID 33425712, 2020). "Together, these data indicated that CTSS plays an important role in tumor autophagy and autophagic flux." (PMID 33425712, 2020). "Previously, several groups have indicated an importance for either tumour infiltrating lymphocyte- (TIL-) derived or epithelial-derived CTSS expression in tumour progression." (PMID 31346333, 2019). "When comparing high versus low CTSS scores, we observed an increase in the number of patients with grade 3 tumours with high CTSS expression in both epithelial (53.39% low versus 84.78% high) and stromal (39.24% low versus 67.76% in high) cells." (PMID 31346333, 2019). "Whilst this study has focused on IHC analysis of resected tumours, others have demonstrated that CTSS levels can be detected in patient serum for a variety of diseases." (PMID 31346333, 2019). "Currently, inhibitory antibodies against CtsS tested in preclinical investigations show a significant reduction of tumor growth and improved chemotherapeutic efficiency." (PMID 31340550, 2019). "Inhibition/depletion of CTSS produced reductions in tumour invasion, burden, proliferation and vascularisation, as well as increased apoptosis." (PMID 31346333, 2019). "Given the association between CTSS expression with macrophages, we decided to examine the expression of activated M1 (tumour destructive) or alternatively activated M2 (tumour protective) macrophage polarisation markers in the context of CTSS expression." (PMID 31346333, 2019). "Cathepsin S-null (cathepsin S−/−) mice crossed with the spontaneous pancreatic beta-cell carcinogenesis model (RIP1-Tag2) exhibited impaired tumor growth and angiogenesis." (PMID 30120227, 2018). "Further insight into the roles of cathepsin S in tumorigenesis has been provided by the upregulation of cathepsin S in various tumor tissues." (PMID 29707130, 2018).
tumor (continued). "For example, combined treatment with Fsn0503 (a cathepsin S inhibitory antibody) and an anti-vascular endothelial growth factor antibody exhibits a synergistic inhibitory effect of angiogenesis in the tumor microenvironment." (PMID 30120227, 2018). "Studies have suggested that cathepsin S promotes tumor invasion through extracellular matrix degradation that release matrix—derived growth factors that drive angiogenesis." (PMID 29516317, 2018). "More recently, a study further demonstrated that a combination of the CTSS inhibitor and the EGFR tyrosine kinase inhibitor markedly promoted tumor apoptosis, indicating that CTSS is a potential novel therapeutic target for cancer treatment." (PMID 28327651, 2017). "MCF7 cells are oestrogen dependent adenocarcinomas that have previously been shown to express CTSS, and have previously been used as a model of tumor invasion in a number of other studies." (PMID 27097645, 2016). "In this report we have described the validation and characterisation of small molecule CTSS inhibitor, compound 6 using activity, cellular and murine tumor models." (PMID 27097645, 2016). "Taken together, CTSS inhibition was shown to block tumor progression, through decreased invasion, decreased proliferation and increased apoptosis, consistent with previous observations." (PMID 27097645, 2016). "We previously observed that cathepsin S (CTSS) inhibition induces tumour cell autophagy through the EGFR-mediated signalling pathway." (PMID 27387133, 2016). "A dual depletion MC38 model has previously been established, whereby both host and tumor CTSS has been depleted, demonstrating a reduction in tumor progression and growth." (PMID 27097645, 2016). "When applied in both MC38 and MCF7 transwell invasion assays, compound 6 demonstrated the ability to reduce tumor cell invasiveness in a manner consistent with pharmacologically blocking CTSS activity." (PMID 27097645, 2016). "In this investigation, we applied a cell-permeable dipeptidyl nitrile inhibitor of cathepsin S, originally developed to target cathepsin S in inflammatory diseases, in both in vitro and in vivo tumor models." (PMID 27097645, 2016). "Cathepsins (CTSs) are multifunctional enzymes that regulate tumor growth, migration, invasion, metastasis, and angiogenesis." (PMID 27031837, 2016). "Genetic ablation studies targeting CTSS has demonstrated reduced tumor progression in murine models." (PMID 27097645, 2016). "We recently demonstrated that inhibiting CTSS activities in tumor cells can rapidly induce autophagy and act as an upstream event for mediating early ROS production through xanthine oxidase (XO)." (PMID 26029922, 2015). "CTSS inhibition not only blocks tumor cell invasion and endothelial tube formation but also induces cellular cytotoxicity." (PMID 26029922, 2015). "Cathepsin S (CTSS), which is highly expressed in various malignant tumor cells, has been proposed to promote tumor progression, migration, and invasion." (PMID 26029922, 2015). "Cathepsin S is a lysosomal cysteine protease that promotes the growth and invasion of tumour and endothelial cells during cancer progression." (PMID 22168338, 2011). "Reports have shown that cathepsin S is stable at neutral pH and is potently elastin- and collagenolytic, promoting extracellular matrix remodelling, tumor growth and invasion in the tumor microenvironment." (PMID 22168338, 2011). "Fsn0503 is a murine IgG1κ antibody, shown to have anti-tumor efficacy in xenograft models through inhibition of cathepsin S mature protein." (PMID 22168338, 2011). "Cathepsin S is a cysteine protease that plays a key role in invasion, angiogenesis and metastasis during tumor progression." (PMID 22168338, 2011). "We have previously shown that the application of an inhibitory antibody to cathepsin S, Fsn0503, can block tumour development." (PMID 20824056, 2010). "Endothelial cathepsin S has been shown to play an important role in the facilitation of tumour angiogenesis." (PMID 20824056, 2010).
tumor (continued). "Taken collectively with our own findings, it suggests that the specific targeting of extracellular cathepsin S will have clinical utility for blocking tumour angiogenesis." (PMID 20824056, 2010). "Cathepsin-B (CTS-B) and Cathepsin–S (CTS-S) are cysteine proteases and have been implicated in ECM remodeling, in particular in processes important for tumor development and progression, including angiogenesis, cell proliferation and invasion." (PMID 21321384, 2010). "Cathepsin S is one of a family of 11 cysteine proteases, many of which have been shown to be up-regulated in tumours." (PMID 20824056, 2010). "Taken together, these studies have highlighted the potential of targeting cathepsin S in the tumour microenvironment." (PMID 20824056, 2010). "Cathepsin S is a cysteine protease that has been shown to play a key role in the development of tumour neovasculature." (PMID 20824056, 2010). "We further show that cathepsin S promotes pericellular hydrolysis of extracellular matrix components in the tumour microenvironment and facilitates endothelial invasion." (PMID 20824056, 2010). "The tumor growth rate of CTSS-knockdown NHRI-HN1 cells was significantly inhibited." (PMID 40707961, 2025). "Notably, tumor weight increased significantly more in the control group than in the CTSS-suppressed cells." (PMID 40794185, 2025). "In some cancer types, CTSS contributes to tumor progression through multifaceted mechanisms." (PMID 40794185, 2025). "CTSS plays a crucial role in tumor progression, metastasis, and angiogenesis." (PMID 40707961, 2025). "On the basis of our in vitro findings, we hypothesized that CTSS expression influences CRC tumor growth through the modulation of tumor immunity." (PMID 40794185, 2025). "The CTSS level was significantly higher in tumor tissue than in normal tissue (p = 0.043)." (PMID 40707961, 2025). "CTSS inhibition also remodeled the memory CD8+ T cell subsets within tumor tissues in vivo." (PMID 40707961, 2025). "ICAM1 antibody‐bound ICG triggers tumor‐specific, caspase‐1‐independent pyroptosis via CTSS‐mediated GSDMD cleavage, activates antitumor immunity, and synergizes with anti–PD‐1 therapy, offering a non‐apoptotic strategy to overcome resistance in cancer treatment." (PMID 40539828, 2025). "CtsZ provided by tumor-associated macrophages is identified as a compensatory protease that can regulate the acquired tumor-promoting function of lesions lacking CtsB and CtsS." (PMID 40129966, 2025). "However, further studies have to be carried out to better understand secretory pathways for CTSs release from tumor cells and EVs-mediated mechanisms in AML disease." (PMID 41227296, 2025). "Interestingly, melittin specifically inhibited tumor cell growth and impeded the activity of cathepsin S in HCC cells and Mock/MHCC97-H cells." (PMID 38318188, 2024). "To test the hypothesis that inhibition of CTSS would increase anti-tumor immune activity, we treated mice implanted with MC38 tumors with a CTSS small molecule inhibitor." (PMID 37173324, 2023). "Notably in cancer, CTSS has been shown to promote tumour progression, primarily through facilitating invasion and migration of tumour cells and augmenting angiogenesis." (PMID 38116078, 2023). "Moreover, using an intrabody approach, we exhibited the ability to express these clones intracellularly and inhibit CTSS activity whilst lead clones were also noted to impede cell invasion in a tumour cell invasion assay." (PMID 38116078, 2023). "Additionally, tumor growth was further decreased in mice treated with the combination of anti-PD-1 and CTSS inhibitor as compared to mice treated with anti-PD-1 or CTSS inhibitor alone." (PMID 37173324, 2023).
tumor (continued). "Besides, up-regulated levels of CTSS in TNBC tissues have been demonstrated to play a critical role in accelerating tumor invasion." (PMID 36803413, 2023). "Indeed, use of recombinant CTSS propeptide has been investigated as a tactic to inhibit tumour advancement." (PMID 38116078, 2023). "Furthermore, BCG hydrogel promoted cathepsin S (CTSS) activity in MΦ and DCs, resulting in enhanced antigen processing and presentation of tumor-associated antigens." (PMID 35732347, 2022). "Cathepsin S is highly expressed in renal clear cell carcinoma, hepatocellular carcinoma, cervical cancer, lung cancer and other tumours and is an essential regulator of tumour growth and invasion." (PMID 35264209, 2022). "Although many studies have demonstrated the vital role of CTSS in many physiological and pathological processes including tumor growth, angiogenesis and metastasis, the function of CTSS in the development of rabbit granulosa cells (GCS) remains unknown." (PMID 34199180, 2021). "Increased probability of tumor node metastasis is associated with the enhanced serum levels of cathepsin S (CTSS) that possess a substantial role during the invasiveness of HCC and CD47 promotes CTSS expression via NF‐κB activation." (PMID 32902664, 2021). "Similarly, other studies have shown that MMP9 and CTSS inhibitors effectively inhibit tumor growth as well." (PMID 34771678, 2021). "Studies have shown that CTSS gene played an important role in lipid metabolism in tumor tissue." (PMID 34199180, 2021). "We tested whether the deletion of CTSS in HSC-3 with CRISPR/Cas9 altered tumor proliferation as measured by tumor volume." (PMID 34572924, 2021). "To determine the potential role of CTSS in the pathogenesis of IgAN, we recruited 25 children with IgAN and 25 age and gender-matched healthy children as well as eight patients with trauma or tumor." (PMID 33912521, 2021). "We then analyzed CTSL and CTSS in plasma to compare systemic and tumor levels." (PMID 33042834, 2020). "In addition to inhibiting tumor invasion and angiogenesis, we found that the inhibition of CTSS in GBC lines induced autophagy and apoptosis and that these effects were strongly related to ROS-mediated PI3K/AKT/mTOR signaling pathways." (PMID 33425712, 2020). "Moreover, antibodies against extracellular fraction of cathepsin S efficiently inhibited tumor growth and neovascularization in xenograft tumors and improved chemotherapy efficacy in colorectal carcinomas." (PMID 32668602, 2020). "CTSS is also highly expressed in various tumor tissues, including GB." (PMID 33425712, 2020). "We found that inhibition of CTSS exert anti-tumor effects both in vitro and in vivo." (PMID 33425712, 2020). "In addition to the overexpression of matrix metalloproteinase-9, SCLC CTC lines release cathepsin S which has been involved in brain metastasis which is frequently observed for this tumor type." (PMID 35582592, 2019). "Finally, analysis of matching IHC analysis reveals an increased M1 (tumour destructive) polarisation in macrophage in patients exhibiting high epithelial CTSS expression." (PMID 31346333, 2019). "Importantly, only the combined depletion of cathepsin S in the tumor and stroma compartment was efficient to reduce BrM burden." (PMID 31396225, 2019). "Like TAMs in the primary tumor, MAMs in metastatic sites also produce proteases to aid tumor cell invasion, such as cathepsin S, which has been shown to degrade the JAM-B junctional adhesion molecule in the blood–brain barrier and enhance breast–brain metastasis in both murine models and patients." (PMID 30200242, 2018). "In conclusion, our results reveal that MP can reduce CTSS expressed level to induce cell cycle arrest, autophagy, and apoptosis in human oral cell lines through mediated p38 MAPK/JNK signaling pathways, suggesting that MP and CTSS are attractive candidates for tumor therapies." (PMID 28327651, 2017).